RRAD (RRAD, Ras related glycolysis inhibitor and calcium channel regulator)
Description:
May regulate basal voltage-dependent L-type Ca(2+) currents and be required for beta-adrenergic augmentation of Ca(2+) influx in cardiomyocytes, thereby regulating increases in heart rate and contractile force (By similarity). May play an important role in cardiac antiarrhythmia via the strong suppression of voltage-gated L-type Ca(2+) currents (By similarity). Regulates voltage-dependent L-type calcium channel subunit alpha-1C trafficking to the cell membrane (By similarity). Inhibits cardiac hypertrophy through the calmodulin-dependent kinase II (CaMKII) pathway. Inhibits phosphorylation and activation of CAMK2D.
Synonyms: RAD; REM3
Tractability: Small molecule: a structure with a bound ligand is known. Antibody: UniProt places it where antibodies can reach, with medium confidence; its Gene Ontology location is reachable by antibodies, with medium confidence; the Human Protein Atlas places it where antibodies can reach. PROTAC: ubiquitination databases record sites on it; its protein half-life has been measured.
Gene: Protein-coding gene on chromosome 16 (66,921,682 to 66,926,308, reverse strand). Ensembl gene ENSG00000166592.
Subcellular location: Cell membrane
Subcellular location (Human Protein Atlas): Plasma membrane; Flagellar centriole; Golgi apparatus; Nucleoplasm
Pathways (Reactome):
Signal Transduction: NGF-stimulated transcription
Gene Ontology:
Molecular function: protein binding; calcium channel regulator activity; GTP binding; GTPase activity
Biological process: small GTPase-mediated signal transduction
Cellular component: cytosol; plasma membrane
Genetic constraint (gnomAD): Loss-of-function variants: 15 observed, 20.55 expected, observed/expected ratio (o/e) 0.73, 90% interval 0.49 to 1.12. The upper end of that interval is the gene's LOEUF score, 1.12, which puts it in group 4 of 6, group 1 being the genes least tolerant of losing a copy. Missense variants: 438 observed, 386.63 expected, observed/expected ratio (o/e) 1.13, 90% interval 1.05 to 1.23. Synonymous variants: 180 observed, 156.03 expected, observed/expected ratio (o/e) 1.15, 90% interval 1.02 to 1.3.
Homologues: Orthologues: chimpanzee RRAD (99% identical), macaque RRAD (98% identical), pig RRAD (95% identical), guinea pig RRAD (93% identical), dog RRAD (93% identical), mouse Rrad (93% identical), rat Rrad (93% identical), rabbit RRAD (68% identical), tropical clawed frog rrad (67% identical), zebrafish rrad (66% identical). Paralogues in human: GEM (55% identical), REM1 (48% identical), REM2 (45% identical), RIT1 (23% identical), RIT2 (22% identical), RASL12 (22% identical), RERG (21% identical), RHEBL1 (20% identical), RRAS2 (20% identical), RASL11B (20% identical), RRAS (20% identical), MRAS (20% identical), and 23 more.
Diseases named in the same sentence as RRAD in open-access papers:
RRAD is named in the same sentence as 51 diseases in open-access papers, as found by Europe PMC text mining. Sharing a sentence is not in itself a finding about the gene and the disease. The quoted sentences say what the papers report.
diabetes (21 papers, 2012 to 2025). "The RRAD gene, which encodes the Ras-related associated with diabetes (RRAD) protein, has been linked to BrS, resulting in changes in RRAD protein function and downstream signaling cascades." (PMID 40722809, 2025). "Knockdown of Ras-related associated with diabetes (RRAD), a GTPase commonly implicated in metabolic function and hepatocellular carcinomas, suppressed cancer cell invasion, proliferation, and EMT." (PMID 36980717, 2023). "We proved that RRAD (RAS associated with diabetes) is a key target gene for SETD8 and that RRAD can promote lipid peroxidation in pancreatic cancer cells." (PMID 36934248, 2023). "Previously, we and others showed that RRAD (Ras-related associated with diabetes, RAD) expression is positively correlated with malignant progression." (PMID 33980886, 2021). "RRAD encodes RAD (Ras associated with diabetes) GTPase, known to play a role in Cav1.2 trafficking and associated with ventricular arrhythmia in mice." (PMID 33802229, 2021). "Ras associated with diabetes (RAD), a membrane protein consists of 308 amino acids, is encoded by human RRAD gene and is highly expressed in cardiomyocytes." (PMID 33195237, 2020). "The RRAD gene encodes a member of the Ras-related GTPase activating proteins family involved in diabetes and glucose metabolism." (PMID 30419821, 2018). "All except phosphodiesterase 2A (PDE2A) and Ras-related associated with diabetes (RRAD) were also differently expressed in diabetic versus healthy left ventricles." (PMID 28727746, 2017). "Other reversed genes included Ras-related associated with diabetes (RRAD) and the tumor necrosis factor receptor superfamily-12A (TNFRS12A)." (PMID 28545403, 2017). "In fact, transfection of the N50-REST cDNA into MRC5 cells modifies the expression profiles of the REST target genes RRAD (Ras-related associated with diabetes) and TMS-1 (target of methylation induced silencing-1)." (PMID 22792276, 2012). "Specifically we examined the Insulin-like Growth Factor Receptor 1, (IGFR1) Mucin 20, (MUC20), Ras Related Associated with Diabetes, (RRAD), and the Phosphoserine Phosphatase (PSPH) genes using qRT-PCR." (PMID 22783543, 2012). "Ras-related associated with diabetes (RRAD, RAD) is a member of small GTP binding family of proteins within the Ras superfamily, sometimes referred to as the RGK family, which was first identified in type II diabetes patients because of its abnormally high expression." (PMID 36979412, 2023). "Consistent with the importance of the nuclear localization of Maid for its tumor suppressor activity, it has recently been reported in human cancer cells that RRAD (ras associated with diabetes) antagonizes Maid’s anti-tumor role by facilitating Maid export from the nucleus to the cytoplasm." (PMID 26107180, 2015). "Through gene expression profiling, we noticed that SETD8 reduces the expression of RRAD, a closely related gene of glycometabolism (RAS associated with diabetes)." (PMID 36934248, 2023). "RRAD was originally identified in the skeletal muscle of patients with type 2 diabetes mellitus 30,31." (PMID 38076903, 2023). "Ras associated with diabetes, a member of the RGK subfamily in the Ras-related GTPase, is encoded by RRAD gene and abundantly expressed in cardiomyocytes." (PMID 33195237, 2020).
type II diabetes (6 papers, 2017 to 2023). "RRAD is a member of the Ras-like small GTPase family, which is initially identified as a gene associated with Type II diabetes." (PMID 28029651, 2017). "RRAD is implicated in several cancers and plays an important role in type II diabetes." (PMID 32784936, 2020). "Increased expression of RRAD has already been widely documented in type 2 diabetes, however, our results indicate that it may also have a significant impact on the pathogenesis of insulin-dependent type of diabetes." (PMID 36091019, 2022).
cardiac hypertrophy (5 papers, 2020 to 2025). "With respect to function, RRAD is a small GTPase reported to negatively regulate L-type calcium channels in the heart, where its deficiency can promote cardiac hypertrophy." (PMID 32515734, 2020). "We focused on the third “calcium signal pathway” for it is closely related to the physiological function of RRAD gene and it has been confirmed as the central mechanism of cardiac hypertrophy in previous studies." (PMID 33195237, 2020).
lung carcinoma (5 papers, 2015 to 2023). "Downregulation of RRAD in lung cancer leads to increased TNFα-stimulated NF-κB target genes such as MMP9, HIF-1α, and GLUT1 at both protein and mRNA levels." (PMID 36979412, 2023). "In lung cancer, RRAD directly bounds to the subunit p65 in the NF-κB complex and negatively regulates the activation of NF-κB by inhibiting p65 translocate to the nucleus." (PMID 36979412, 2023). "In current study, using double directional genetic manipulation in well-established lung cancer cell lines, we showed that both E6 and E7 down-regulated the expression of RRAD at both protein and mRNA levels." (PMID 31839825, 2019). "The expression of RRAD and p65 in four lung cancer cell lines, H1299, A549, LK2, and H460 were screened." (PMID 31839825, 2019). "In this study, we showed that the overexpression of E6 or E7 in lung cancer cell lines down-regulated the expression of RRAD at both the protein and mRNA levels." (PMID 31839825, 2019). "Our findings provided new evidence to support the critical role of RRAD in the pathogenesis of HPV-related lung cancer, and suggested novel therapeutic targets." (PMID 31839825, 2019). "Recent studies have revealed that RRAD also has tumor suppressive function in many types of cancers, and RRAD is frequently down-regulated in multiple cancers including lung cancer, due to the hypermethylation of its promoter region." (PMID 28029651, 2017). "Accumulating evidence suggests that the RRAD promoter is hypermethylated in human cancers, such as nasopharyngeal carcinoma, breast cancer, esophageal cancer, glioblastoma, cervical carcinoma, ovary cancer, and lung cancer." (PMID 36979412, 2023). "Meanwhile, ectopic RRAD expression could inhibited the nasopharyngeal carcinoma cell growth and cell migration, and negatively regulates the NF-κB signaling to inhibit the GLUT1 translocation and the Warburg effect in lung cancer cells." (PMID 28029651, 2017).
breast carcinoma (4 papers, 2012 to 2023). "Some of the known oncogenic genes on 16q22 are RRAD, a member of the Ras family, known to be associated with several cancers including breast cancer, leukemia, lymphoma, and glioma." (PMID 34178034, 2021). "Overexpression of RRAD in breast cancer is associated with invasiveness and poor prognosis." (PMID 31857616, 2019). "Overexpression of RRAD in the breast cancer cells results in acceleration of cell cycle transition which is dependent on its NH2- and COOH-terminal regions which contain CaM." (PMID 36979412, 2023). "RRAD is also expressed in some malignant tumors such as breast cancer, leukemia, lymphoma, and glioma." (PMID 31857616, 2019). "In addition, RRAD was identified as a negative regulator of the Warburg effect and cancer progression in breast cancer, nasopharyngeal cancer, hepatocellular carcinoma, and lung cancer." (PMID 31857616, 2019).
glioma (4 papers, 2013 to 2023). A benign or malignant brain and spinal cord tumor that arises from glial cells (astrocytes, oligodendrocytes, ependymal cells). "Analysis of gene expression of human glioma tissue samples deposited in the REMBRANDT database revealed a correlation between upregulation of RRAD in EGFR-expressing glioma patients and poorer prognosis." (PMID 33980886, 2021). "Therefore we further validated RRAD overexpression in EGFR high human glioma specimens." (PMID 33980886, 2021). "However, analysis of gene expression in EGFR-low human glioma tissue samples did not reveal a correlation between upregulation of RRAD and poorer prognosis." (PMID 33980886, 2021).
Insulin resistance (4 papers, 2019 to 2022). Increased resistance towards insulin, that is, diminished effectiveness of insulin in reducing blood glucose levels. "The over expression of RRAD inhibits the glucose uptake and is associated with insulin resistance and T2DM." (PMID 32823525, 2020). "In addition, insulin resistance was demonstrated to coexist together with overexpression of RRAD in isolated muscle cells." (PMID 36091019, 2022). "An in vivo study of transgenic mice overexpressing RRAD in skeletal muscle found that high-fat feeding produced not only insulin resistance in transgenic mice, but also increased triglyceride metabolism compared to controls." (PMID 31557856, 2019).
Brugada syndrome (3 papers, 2023 to 2025). A genetically heterogeneous condition characterized by complete or incomplete right bundle branch block accompanied by ST elevation in leads V1-V3. "In particular, a gain of function RRAD mutation has been associated though an hiPSC model to a familial case of Brugada syndrome, a channelopathy exhibiting right bundle branch block and slowed cardiac conduction." (PMID 39227896, 2024).
nasopharyngeal carcinoma (3 papers, 2017 to 2019). A carcinoma arising from the nasopharyngeal epithelium. "Transfection of RRAD in cancer cells suppressed cell proliferation, colony formation, and migration, suggesting that RRAD has tumor-suppressive functions in nasopharyngeal carcinoma." (PMID 30340457, 2018).
pancreatic cancer (3 papers, 2023 to 2024). "Mechanistically, SETD8 inhibits the transcriptional activity of RRAD by binding to the promoter region of RRAD, thus downregulating the expression of RRAD and resulting in a decrease in the incidence of ferroptosis in pancreatic cancer cells." (PMID 36934248, 2023). "The combination of SETD8 and the RRAD promoter subregion results in the inhibition of RRAD transcription, thereby affecting the occurrence of erroptosis in pancreatic cancer." (PMID 36934248, 2023). "In general, SETD8 inhibits RRAD transcription by interacting with the RRAD promoter, thus inhibiting ferroptosis in pancreatic cancer cells." (PMID 36934248, 2023). "Meanwhile, low expression of RRAD is closely related to poor prognosis of pancreatic cancer patients." (PMID 36934248, 2023). "Our further experiments show that SETD8 inhibits RRAD transcription and that the SETD8 knockout-induced increase in lipid peroxidation levels in pancreatic cancer cells can be reversed by silencing RRAD gene expression." (PMID 36934248, 2023). "By analysing the results of the following functional analysis, and we found that compared with the control group, the ability of RRAD-overexpressing cell lines to proliferate and form colonies decreased significantly, indicating that RRAD inhibited the proliferation of pancreatic cancer cells." (PMID 36934248, 2023). "Furthermore, we found that SETD8 inhibited the ferroptosis in pancreatic cancer by binding to the promoter region of RRAD, revealing the role of SETD8-RRAD-ferroptosis axis in the regulation of pancreatic cancer." (PMID 36934248, 2023). "This indicates that RRAD can promote the occurrence of ferroptosis in pancreatic cancer." (PMID 36934248, 2023). "The expression of RRAD was closely related to the prognosis of pancreatic cancer patients." (PMID 36934248, 2023). "Therefore, high levels of SETD8 and low levels of RRAD are closely related to poor prognosis in pancreatic cancer patients." (PMID 36934248, 2023). "This indicates that RRAD promotes the occurrence of ferroptosis in pancreatic cancer cells." (PMID 36934248, 2023). "SETD8 interacts with the promoter region of RRAD, which epigenetically silences the expression of RRAD to reduce the level of lipid peroxidation in pancreatic cancer cells, thereby inhibiting ferroptosis in pancreatic cancer cells and resulting in poor prognosis of pancreatic cancer." (PMID 36934248, 2023). "We also constructed stable pancreatic cancer cell lines that stably expressed SETD8 and RRAD and overexpressed SETD8 and RRAD in MIA PaCa-2 cell lines." (PMID 36934248, 2023). "To further study the function of RRAD in the development of pancreatic cancer, we overexpressed RRAD in the MIA PaCa-2 cell line and confirmed the efficiency of RRAD over expression by qPCR and Western blotting." (PMID 36934248, 2023).
glioblastoma (2 papers, 2021 to 2023). The most malignant astrocytic tumor (WHO grade IV). "High expression of RRAD is clearly implicated in the malignant progression of human glioblastoma." (PMID 33980886, 2021). "Drug screening led to the isolation of compounds with selective activity towards RRAD-overexpressing glioblastoma cells (LN229-RRAD) in tumorsphere formation assays." (PMID 33980886, 2021). "In this study, we have shown that oxelaidin, an antitussive agent, effectively inhibits glioblastoma through targeting RRAD." (PMID 33980886, 2021). "To identify RRAD inhibitors, we used a cell-based assay with a high RRAD-expressing glioblastoma cell line for screening ~ 2000 clinical compounds as a drug repositioning strategy." (PMID 33980886, 2021). "In view of its pro-tumorigenic role in glioblastoma, RRAD may serve as a promising target for therapeutic intervention." (PMID 33980886, 2021). "RRAD expression is reported to promote cell survival via activation of the EGFR/STAT3 signaling pathway and stimulate glioblastoma cell migration." (PMID 33980886, 2021). "Given that RRAD knockdown sensitizes chemo-resistant cancer cells to cytotoxic drugs, targeting STAT3 with oxeladin or butamirate may attenuate temozolomide resistance and glioblastoma recurrence after treatment." (PMID 36979412, 2023). "Given that RRAD induces EGFR and STAT3 activation and RRAD knockdown sensitizes chemoresistant cancer cells to cytotoxic drugs, targeting STAT3 with oxelaidin or butamirate may attenuate temozolomide resistance and glioblastoma recurrence after treatment." (PMID 33980886, 2021).
prostate carcinoma (2 papers, 2022 to 2023). A carcinoma that arises from epithelial cells of the prostate gland. "Previous work identified RRAD as an early growth response protein 1/2 (EGR1/2) target gene, and EGR expression levels are positively related to RRAD expression levels in prostate cancer." (PMID 36979412, 2023).
Arrhythmia (1 paper, 2024). Any cardiac rhythm other than the normal sinus rhythm. "RNA-seq analysis in this study revealed upregulation of the calcium channel regulator RRAD in the M1 coculture condition, which is notable as this gene has previously been linked to arrhythmia." (PMID 39227896, 2024).
breast tumor (1 paper, 2020). "In addition, a report from 2001 indicated that RRAD is sufficient to promote proliferation of breast tumor cells in vitro and in vivo." (PMID 32515734, 2020).
cervical cancer (1 paper, 2015). A primary or metastatic malignant neoplasm involving the cervix. "It was reported that MT1G, NMES1, RRAD, SFRP1, SPARC and TFPI2 were more often methylated in invasive cervical cancer samples than in normal ones, suggesting that these 6 genes may be potential tumor suppressor candidate for cervical cancer." (PMID 26329329, 2015).
congestive heart failure (1 paper, 2023). Failure of the heart to pump a sufficient amount of blood to meet the needs of the body tissues, resulting in tissue congestion and edema. "RRAD is predicted to be involved in small GTPase-mediated signal transduction, it has been implicated in some types of cancer and is considered a biomarker of congestive heart failure." (PMID 38137449, 2023).
endometrial cancer (1 paper, 2012). Primary or metastatic malignant neoplasm involving the endometrium (mucous membrane that lines the endometrial cavity). "Data from these assays performed on a panel of endometrial cancers from AA and CA confirmed the array findings for IGF1R, MUC20, and RRAD, but interestingly, qRT-PCR utilizing primers targeted to PSPH did not." (PMID 22783543, 2012).
gastric cancer (1 paper, 2023). A primary or metastatic malignant neoplasm involving the stomach. "RRAD inhibition could also suppress expression of EMT-associated proteins (VIMENTIN, TWIST, SNAIL, and OCCLUDIN), VEGF, and ANGP2 in gastric cancer (GC) and colorectal cancer (CRC) cell lines." (PMID 36979412, 2023).